ENSG00000259002 (novel transcript)
Gene: Long non-coding RNA gene on chromosome 14 (34,541,740 to 34,557,282, reverse strand). Ensembl gene ENSG00000259002.
Gene Ontology:
Molecular function: pre-mRNA 5'-splice site binding
Biological process: mRNA 5'-splice site recognition
Cellular component: U1 snRNP